INS (insulin)
Diseases named in the same sentence as INS in open-access papers (continued):
Sharing a sentence is not in itself a finding about the gene and the disease.
Hyperglycemia (continued). "The actions of insulin on glucose metabolism are mediated by PI3K so it is not surprising that in clinical trials, hyperglycemia was a common effect of many early pan PI3K inhibitors, as well as dual-specificity PI3K/mTOR inhibitors and PI3Kα-specific inhibitors." (PMID 31443495, 2019). "In absence of impaired insulin sensitivity in sedentary SMA mice, we asked whether hyperglycemia and glucose intolerance could be due to an impaired insulin secretion." (PMID 31632295, 2019). "Secondly, the development of IGF neutralizing antibodies provides a means of blocking IGF-1R and INSR-A without compromising insulin signaling via INSR-B, thereby avoiding dose-limiting hyperglycemia that contributed to adverse outcomes in IGF-1R inhibitor trials." (PMID 31416218, 2019). "Perinatal deaths could be secondary to longer exposure to hyperglycaemia, as we found that non-insulin-treated women with GDM had a later term of delivery compared with insulin-treated women." (PMID 28197657, 2017). "During the first week of life, hyperglycemia (blood glucose=250 mg/dL) without ketoacidosis was observed, and treatment with subcutaneous NPH insulin was initiated on the 7th day of life, followed by continuous subcutaneous insulin infusion." (PMID 28663161, 2017). "Caution must also be taken during sample taking as the animal should not be stressed (resulting in hyperglycemia, increased NEFA/insulin) and the moment of the day may also modify these metabolite concentrations." (PMID 28107442, 2017). "Additionally, serum AGE levels are positively correlated with testosterone level, free androgen index, insulin, HOMA and waist-to-hip ratio in women with PCOS who did not have hyperglycemia." (PMID 27769286, 2016). "Third, because serum insulin was not available in the CNSR, we could not identify the precise action of hyperglycemia status alone on the prognosis of minor stroke." (PMID 27070309, 2016). "Correction of hyperglycemia with a non-selective SGLT inhibitor, phlorizin, normalizes insulin sensitivity in partially pancreatectomized diabetic rats with moderate glucose intolerance and non-insulin-dependent diabetic rats induced by neonatal streptozotocin." (PMID 25615826, 2015). "Although GLUT4 is the major GLUT isoform in insulin-sensitive tissue, GLUT4 knockout mice do not develop hyperglycemia, suggesting that other GLUT isoforms may be involved in the regulation of whole-body glucose homeostasis." (PMID 26539824, 2015). "However the hyperglycemia observed in the neonates following STZ is only transient and the plasma glucose and insulin values are no longer significantly different from those of control." (PMID 24734054, 2014). "Some patients taking 1 daily dose of basal insulin (NPH, detemir, or glargine) may not achieve the proposed A1C targets due to postprandial hyperglycemia despite appropriate fasting BG levels." (PMID 24011173, 2013). "It is to be determined whether or not POMC is involved in improvement on hyperglycemia in our model since POMC regulates glucose homeostasis and insulin sensitivity through distinct CNS populations from those regulating food intake and body weight." (PMID 23326534, 2013). "In agreement with other reports, glucose injection did not stimulate any significant increase in circulating insulin at the intervals measured (24H-SIG), making this a clear determination of the insufficiency of hyperglycemia alone to induce glycogen over-accumulation in IBAT." (PMID 23861810, 2013). "N-STZ females that required insulin before mating had non-fasting glucose values significantly higher than control (N-STZ: 18.4±6.10 mmol/l, vs C: 6.05±0.61 mmol/l, p<0.001) and pronounced hyperglycemia in response to glucose." (PMID 23691181, 2013). "However, chronic constant fetal hyperglycemia for longer than eight days results in an unequivocal decrease in GSIS and ASIS, not explainable by plateau glucose-stimulated insulin concentrations." (PMID 23133755, 2012).
Hyperglycemia (continued). "To gain mechanistic insights into whether OC could restore pancreatic gene expression of insulin and PDX1 under conditions of hyperglycemia, we further examined the gene expression of FOXO1, PDX1 and insulin in β-cells cultured with OC, with or without the AKT inhibitor." (PMID 40585255, 2025). "Compared with patients who only had nocturnal hypoglycemia that was not followed by hyperglycemia (n = 332), patients with PHNH were younger, were less frequently diagnosed as latent autoimmune diabetes in adults (LADA), and used higher total daily doses of insulin." (PMID 40465171, 2025). "This study showed that blood glucose, insulin, HOMA-IR, TG, LDL-C, TCHO, IL-1β, TNF- α showed marked elevation in T2D mice, suggesting that there is hyperinsulinemia and IR in T2D, the body is in an inflammatory state, insulin can not be used normally, which is manifested as hyperglycemia." (PMID 41098781, 2025). "Our data indicated a downregulation of hyperglycaemia‐induced αSMA by Sirt7 overexpression supplemented with glucose normalization, which increased the hyperglycaemia‐mediated reduction of HIC1, SDC1 and CD31 expression in the kidneys of the rats, while insulin alone did not work." (PMID 38686489, 2024). "However, the ability of ESA to improve diabetic rats’ body weight, even in the absence of insulin, could be explained by the protective effect of ESA on hyperglycemia-mediated toxicity and cell death in other tissues." (PMID 37893548, 2023). "Furthermore, our data suggest that insulin therapy can be safely continued in these patients while on ICI treatment, including through steroid treatment for other IRAEs, without adverse outcomes related to hyperglycemia or DKA." (PMID 38027216, 2023). "The absence of a maternal hyperglycemia effect may be due, in part, to increases in POMC expression in the ARC that were observed following maternal hyperglycemia and HFD exposure, which might increase insulin sensitivity and, thus, glucose tolerance." (PMID 37396180, 2023). "The primary aim of this trial was to evaluate if a strict glucose intervention with insulin infusion monitored with a hybrid approach of isCGM and periodic POC is safe, practical, and beneficial in a surgical, non-ICU ward setting during TPN-induced hyperglycaemia." (PMID 37540239, 2023). "Additionally, a ModCHO diet may have supported glycogen repletion without promoting hyperglycemia, thereby facilitating CHO availability and reducing the need for pre-exercise insulin reduction." (PMID 37999431, 2023). "The incidence of hyperglycemia increased in a dose-dependent manner following CYH33 administration, but was effectively managed by appropriate interventions, including dose interruption/reduction and concomitant oral antidiabetic medications, with or without insulin." (PMID 36385120, 2022). "However, having established a positive glucose-lowering effect of the ketogenic diet in healthy rats, we investigated whether ketogenic diet consumption, in the absence of insulin supplementation, would improve STZ-induced hyperglycemia." (PMID 36676967, 2022). "Insulin is also required, in the first instance, for treatment of SIH, as reported in NICE recommendations, but it is frequently not enough to control acute hyperglycaemia because it is not able to suppress glucagon secretion, which is one the principal causes of SIH." (PMID 33466656, 2021). "Furthermore, the degree of AAA expansion and pathophysiological changes in diabetic mice treated with insulin were greater than those of diabetic AAA mice not treated with insulin, suggesting that hyperglycemia can limit the development of experimental aortic aneurysms." (PMID 33614752, 2021). "Thus, insulin plays an essential role in the tumorigenesis of EC via the PI3K-AKT pathway, consistent with accumulating epidemiological studies indicating that hyperinsulinemia, rather than hyperglycemia, plays essential roles in the development of EC." (PMID 32842547, 2020).
Hyperglycemia (continued). "Hepatic lncSHGL restoration reduced triglyceride content and improved hyperglycemia, insulin resistance, and steatosis in obese diabetic mice by activating the PI3K/Akt pathway and repressing the mammalian/mTOR/SREBP-1c pathway independent of insulin and calcium." (PMID 32765426, 2020). "However, insulin signaling is also required for survival and function of healthy cells in vivo, such as podocytes, key cells in DKD, and selective podocyte insulin resistance reproduces features of DKD in the absence of hyperglycemia." (PMID 28060743, 2017). "Furthermore, increased expression of carbohydrate responsive element binding protein (ChREBP), an additional transcription factor whose expression is primarily regulated by the presence of sugars rather than insulin, is seen in NAFLD as a result of hyperglycaemia." (PMID 27632189, 2016). "Absence of HISS action results in postprandial hyperglycemia, hyperinsulinemia, hyperlipidemia, adiposity, increased free radical stress and a cluster of progressive metabolic and cardiovascular dysfunctions referred to as the AMIS (absence of meal-induced insulin sensitization) syndrome." (PMID 25569521, 2015). "This could be interpreted as if it was the chronic hyperglycaemia, rather than the compensating hyperinsulinemia, the mayor player of this effect, since HFD mice exhibit even higher insulin levels than db/db mice of the same age, and only slightly increased glycaemia." (PMID 24586614, 2014). "In addition, the association between macrosomia and T2DM, independent of GDM status, could be attributed to maternal hyperglycemia, which is less overt than GDM and can lead to fetal hyperglycemia, exaggerated fetal insulin response, and macrosomia." (PMID 24050526, 2013).
type 1 diabetes (6,136 papers, 1996 to 2026). "Type 1 diabetes is caused by autoimmune destruction of insulin-secreting β-cells within islets of Langerhans." (PMID 42274585, 2026). "Type 1 diabetes is an autoimmune disease that results in destruction of pancreatic β cells and leads to insulin deficiency, necessitating exogenous insulin administration to regulate blood glucose levels." (PMID 41601938, 2026). "Residual endogenous insulin secretion, reflected by measurable C-peptide, has been linked to improved glycaemic management in type 1 diabetes." (PMID 41165798, 2026). "Type 1 diabetes (T1D) is a chronic autoimmune disease that results in loss of insulin-secreting pancreatic β-cells in the islets of Langerhans." (PMID 41821267, 2026). "In type 1 diabetes, insulin-reactive CD4+ T cells have been implicated in autoimmune pathophysiology." (PMID 40821816, 2025). "We took steps to apply inclusion criteria that would capture valid diagnoses, such as considering insulin prescriptions to reduce the risk of erroneously including type 1 diabetes cases." (PMID 40140545, 2025). "STZ treatment induces hallmark features of type 1 diabetes in experimental animals by selectively destroying pancreatic β-cells, the only source of circulating insulin." (PMID 40806520, 2025). "Type 1 diabetes is an autoimmune disease caused by the host immune system destroying insulin‐producing pancreatic beta cells in response to a foreign antigen in a genetically susceptible person." (PMID 40735262, 2025). "Type 1 diabetes (T1D) is a chronic metabolic disorder characterized by insulin deficiency resulting from autoimmune destruction of insulin‐producing pancreatic cells." (PMID 40344470, 2025). "Type 1 diabetes (T1D) is a chronic autoimmune disease, characterized by the destruction of the pancreatic islet beta cells, leading to loss of insulin production." (PMID 40427033, 2025). "Type 1 diabetes mellitus (T1DM) is an autoimmune disease linked to insufficient insulin production and is brought on by the dysregulation of pancreatic islet b-cells, which is mediated by T-cells." (PMID 41361288, 2025). "Type 1 diabetes is considered an autoimmune condition that results from the destruction of insulin-producing β-cells, causing the body to be unable to produce insulin." (PMID 39563945, 2025). "As automated insulin delivery becomes established as the standard of care in type 1 diabetes, rates of SH and associated risk factors are likely to change and will become a key focus for future research." (PMID 40386839, 2025). "In people with Type 1 diabetes (T1D), this dysregulation is caused by the loss of insulin-producing pancreatic beta cells due autoimmune dysfunction." (PMID 40565059, 2025). "Type 1 diabetes is caused by an autoimmune process that destroys pancreatic islet β cells, resulting in a marked deficiency of insulin." (PMID 40650275, 2025). "More importantly, most of the existing literature regarding interventions to improve skeletal muscle and bone in type 1 diabetes is based on insulin-deficient male mice, whereas our study includes female mice." (PMID 40575255, 2025). "Individuals with type 1 diabetes must receive continuous insulin therapy due to the loss of insulin production in their pancreas." (PMID 41280745, 2025). "In type 1 diabetes, there is an absolute deficiency of insulin; insulin treatment should start from diagnosis for optimal glucose control and maintaining HbA1c." (PMID 40242444, 2025). "Type 1 diabetes is a severe lifelong autoimmune disease characterised by loss of endogenous insulin production." (PMID 41255955, 2025). "Similar benefits have been seen with exercise in the bone phenotype of insulin-deficient rodents and humans with type 1 diabetes." (PMID 40575255, 2025). "Studies show that exercise helps maintain a healthy body weight, improves lipid profile, increases insulin sensitivity, and reduces the risk of metabolic disorders, including type 1 diabetes." (PMID 41479473, 2025).
type 1 diabetes (continued). "Type 1 diabetes is characterized by immune-associated destruction of insulin producing pancreatic beta cells resulting in a lifelong reliance on insulin replacement." (PMID 41285865, 2025). "Type 1 diabetes (T1D) is perceived as a chronic immune-mediated disease characterized by selective loss of insulin-producing β cells in the pancreatic islets of genetically susceptible individuals." (PMID 40195977, 2025). "Type 1 diabetes (T1D) is defined by a near-complete loss of circulating insulin and dysregulated glucagon secretion." (PMID 41026524, 2025). "(STZ)-induced diabetic rat model closely resembles the pathophysiology of type 1 diabetes, characterized by a deficiency in insulin production due to autoimmune destruction of pancreatic β-cells." (PMID 40603345, 2025). "Loss of circulating insulin resulting from autoimmune destruction of β cells is the defining characteristic of type 1 diabetes (T1D), but islet dysfunction in T1D affects both β cells and α cells." (PMID 41321312, 2025). "A low level of insulin has also been observed in glucagon+ α-cells of insulin-deficient islets of individuals with longstanding type 1 diabetes." (PMID 41598174, 2025). "Type 1 diabetes (T1D) is an autoimmune disease caused by T-cell mediated destruction of the pancreatic insulin-producing beta cells." (PMID 40149920, 2025). "Type 1 diabetes (T1D) is a progressive autoimmune condition that culminates in loss of insulin-producing beta cells." (PMID 40585213, 2025). "The role of glucagon-like peptide-1 receptor agonists in type 1 diabetes has been investigated using exenatide and liraglutide, which have been reported to reduce insulin requirements, promote weight loss, and improve HbA1c levels." (PMID 40429740, 2025). "In a cross‐sectional study from two large centres in the US, Ferm and colleagues also showed that insulin pump use in type 1 diabetes was independently associated with a lower likelihood of diabetic retinopathy." (PMID 40390300, 2025). "This condition is triggered by the dysregulation of insulin activity caused by either the destruction of pancreatic β-cells by the immune system for type 1 diabetes (T1DM) or by β-cell dysfunction leading to insulin resistance in type 2 diabetes (T2DM)." (PMID 41471078, 2025). "In our cohort of patients with type 1 diabetes over five years, insulin pump use was associated with lower all‐cause mortality and risk of DKA." (PMID 40390300, 2025). "Type 1 diabetes is a chronic autoimmune disease characterised by insulin deficiency that requires intensive insulin therapy to maintain optimal blood glucose levels." (PMID 40270713, 2025). "Type 1 diabetes (T1D) is a chronic and autoimmune disorder associated with β-cell dysfunction, characterized by an abnormal production of insulin, resulting in high blood glucose values." (PMID 40303945, 2025). "The autoimmune destruction of these cells leads to a deficiency of insulin which is the mechanism behind type 1 diabetes." (PMID 40710848, 2025). "The prevalence of sarcopenia is high in individuals with type 1 diabetes, a condition of insulin deficiency, and the finding that sarcopenia occurs when Chrebp deficiency occurs in an insulin-deficient state is new insight." (PMID 41373820, 2025). "As is already known, patients with type 1 diabetes have a total deficiency of insulin secretion due to the destruction of pancreatic beta cells and are in need of exogenous administration of insulin via basal and prandial doses." (PMID 41462804, 2025). "Gene–gene interactions were noted between GIMAP4 and IL2RA, a known human type 1 diabetes risk gene, as well as between GIMAP5 and INS, a major type 1 diabetes risk gene strongly associated with insulin autoantibodies as the first appearing islet autoantibody." (PMID 41042382, 2025). "Type 1 diabetes (T1D) is an autoimmune disease caused by the selective destruction of the insulin-producing β cells within the islets of Langerhans in the endocrine pancreas." (PMID 40759576, 2025).